EFNA1 (ephrin A1)
Diseases named in the same sentence as EFNA1 in open-access papers (continued):
Sharing a sentence is not in itself a finding about the gene and the disease.
tumor (continued). "In addition, the AUC of EFNA1 and MMP13 for diagnosing GC were 0.723 and 0.761, respectively, while the AUC of GC using both two tumor markers was 0.794." (PMID 38987376, 2024). "In this study, we found that downregulation of EFNA1 could significantly inhibited ESCC cell proliferation, migration and tumor growth in mouse model, suggesting a promoting role of EFNA1 on ESCC progression." (PMID 37160815, 2023). "Tumor-derived ephrin-A1 is completely distinguishable from physiological soluble ephrin-A1 in experimental mouse models but not in pathological conditions in human." (PMID 33804570, 2021). "Tumor cells showed characteristics of Epithelial-Mesenchymal Transition (EMT) and a high expression of EPHA2 (but not ephrin-A1), using IHC, suggesting a possible link between the receptor and aggressive tumor phenotypes." (PMID 34445116, 2021). "The findings also indicate that miR-1224-5p inhibits cell proliferation, colony formation, migration and invasion in vitro and tumour growth in vivo by targeting TNS4, and subsequently promoting the autophagic degradation of EGFR, and suppressing downstream EFNA1/EPHA2 and VEGFA signalling pathways." (PMID 32732965, 2020). "While primary tumor growth did not significantly differ between ephrin-A1 wild-type (Efna1+/+), heterozygous (Efna1+/-), and knockout (Efna1-/-) mice, metastasis and primary tumor recurrence were significantly decreased inEfna1-/- mice." (PMID 32399207, 2020). "Although we did not observe significant differences in tumor immune infiltrate, this does not preclude a role for ephrin-A1 in these cell populations." (PMID 32399207, 2020). "Tumor progression was significantly suppressed by LEF at a dosage of 20.0 mg/kg/day compared to each vehicle control group, and tumor progression in the ephrin-A1-overexpressing group upon LEF treatment was significantly higher than that in empty vector-transfected TCCSUP group under LEF treatment." (PMID 29367676, 2018). "Ephrin-A1 overexpression could partially reverse LEF-induced suppression of angiogenesis and subsequent tumor growth inhibition." (PMID 29367676, 2018). "We found Ephrin B3, Ephrin A1 and EphA2 all to have higher expression in tumor tissue relative to surrounding non-tumorous tissue." (PMID 27533087, 2016). "Only 56 of 206 (27.2%) tumor cases were negative for EFNA1, whereas 91 (44.2%) demonstrated a weak and 59 (28.6%) a moderate to strong positivity for EFNA1." (PMID 25025847, 2014). "Importantly, a significant association was also found between expression of S100A4 and ephrin-A1 in primary tumor samples from NSCLC patients, indicating that S100A4 stimulates ephrin-A1 expression both in vivo and in vitro." (PMID 22853000, 2012). "Based on the reported biological effects of ephrin-A1 and osteopontin, S100A4-induced expression of these molecules may be one of several mechanisms by which S100A4 promotes tumor progression." (PMID 22853000, 2012). "EFNA1 may drive tumor progression via the MAPK signaling pathway, CXCL8 could influence immune evasion through NOD-like receptor signaling, and PPP1R14A may contribute to tumor invasion by modulating extracellular matrix remodeling." (PMID 40406253, 2025). "Tumor-derived ephrin-A1 in urine was observed in some, but not all mice." (PMID 33804570, 2021). "However, EFNA1 expression in ESCA and its relationship with the prognosis of patients, as well as its role in tumor progression, remain unclear and need further study." (PMID 34399788, 2021). "This suggests that the function of ephrin-A1is cell type-dependent and that if there is a way to target ephrin-A1 in host tissues, rather than in the tumor, targeting host ephrin-A1 to inhibit metastasis may be a strategy worth considering." (PMID 32399207, 2020).
tumor (continued). "Similar to the results we obtained from the 4T1 primary tumors, we did not see significant differences in immune populations in tumor-bearing lungs harvested fromEfna1+/+,Efna1+/-, andEfna1-/- littermates, except for a modest increase in macrophages in knockout mice.Underlying data are available." (PMID 32399207, 2020). "Previously, EFNA1 and TFRC have been proposed as prognostic factors in CESC and were found to be sensible to natural compounds – it was shown, that (-)-epigallocatechingallate and curcumin treatment, similar to SM, significantly decrease expression of EFNA1 and TFRC in tumor cells, respectively." (PMID 31523389, 2019). "Second, elevated expression of EphA2 receptor, not ephrin-A1, was notable in the neoplastic cells, suggesting morphological changes reminiscent of epithelial–mesenchymal transition and ligand-independent promotion of tumor cell migration and invasion." (PMID 24606764, 2014). "One could speculate that tumor cells with an “aggressive” expression status, i.e. over-expression of EPHA1 and EPHA2 as well as down-regulation of EFNA1, possess a survival advantage under adverse conditions and thus, are capable of thriving in the foreign microenvironment of secondary sites." (PMID 25025847, 2014). "Although eNOS/NO have been considered as a vital effector in tumor angiogenesis, no previous studies have addressed whether eNOS/NO mediate ephrin-A1-induced angiogenesis." (PMID 24040255, 2013). "However, the regulating factors and mechanisms by which ephrin-A1/EphA2 promote tumor angiogenesis were not well clarified." (PMID 24040255, 2013). "The aim of the present study was to investigate whether S100A4 induces expression of ephrin-A1 and osteopontin in NSCLC, and to characterize the expression of these molecular markers in primary tumor tissue from prospectively recruited patients undergoing curative surgery for NSCLC." (PMID 22853000, 2012). "However, silencing cdx-2 gene with siRNA and subsequent activation with ephrin-A1 or transfection with pcDNA-EFNA1 failed to inhibit tumor growth in A549 cells." (PMID 22824143, 2012). "However, if receptor EphA2 activation with ephrin-A1 induced expression of cdx-2 plays any role in NSCLC tumor growth is not known." (PMID 22824143, 2012). "Therefore, it is not surprised to suppose that eNOS/NO may also mediate ephrin-A1-induced tumor angiogenesis." (PMID 24040255, 2013). "The positive rate of serum EFNA1 + MMP13 was not significantly correlated with clinical data such as age, gender, depth of tumor invasion, lymph node status, TNM stage, early-stage or late-stage GC (all P > 0.05)." (PMID 38987376, 2024). "Ephrin-A1 expression, although higher in CRC tissues compared with normal ones, was correlated to early-stage cancers and smaller tumor size." (PMID 34445116, 2021). "However, we could not detect tumor-derived ephrin-A1 in the urine of all tumor-bearing mice." (PMID 33804570, 2021). "This might be explained by the pro-oncogenic function of EPHA2 in the absence of EFNA1, whereas activation of EPHA2 by EFNA1 promoted tumor suppression by triggering receptor degradation." (PMID 25025847, 2014).
cancer (63 papers, 2010 to 2025). A tumor composed of atypical neoplastic, often pleomorphic cells that invade other tissues. "EFNA1 is highly induced under hypoxic stress through HIF‐dependent pathways in cancer cells, and elevated EFNA1 expression is generally linked with an unfavourable prognosis in solid tumours." (PMID 39245797, 2024). "Overexpression in cancer tissues of all of the ligands studied (ephrin-A1, -A5, -B1, and -B2) was linked to adverse clinical outcomes and dismal prognoses." (PMID 34445116, 2021). "Decreased GFP+ 4T1 cells were found in ephrin-A1-deficient lungs compared to wild-type controls, suggesting that fewer cancer cells had extravasated into the lung parenchyma at this timepoint." (PMID 32399207, 2020). "In conclusion, host deficiency in ephrin-A1 inhibits metastasis by providing a less hospitable metastatic niche for cancer cell extravasation and colonization of the lung." (PMID 32399207, 2020). "Once released, sEV-associated EphA2 promotes cancer cell proliferation by activating the Erk pathway through EphA2/ephrin-A1 reverse signalling." (PMID 28585531, 2017). "High levels of EFNA1 protein have also been reported in vulvar, cervical and gastric carcinomas being associated with advanced and aggressive tumors." (PMID 25025847, 2014). "EFNA1 has been associated with various cancers, and it has been observed to be overexpressed in gastric, colorectal, hepatocellular, renal, cervical, ovarian, esophageal, and laryngeal cancer; this provides further evidence of its significance in the process of oncogenesis." (PMID 40004552, 2025). "Furthermore, pan-cancer analyses have indicated that EFNA1 and its family members are closely associated with immune cell infiltration in the TME, highlighting their potential role in immune evasion." (PMID 40787466, 2025). "In cancer, EphA2 undergoes an oncogenic switch and a loss of dependence on its ligand Ephrin A1." (PMID 38072918, 2023). "EFNA1-5 showed a significant association with the immune subtype in pan-cancer (p < 0.001)." (PMID 35309935, 2022). "However, a high protein expression of EFNA1 was linked to poor survival in patients with vulvar and cervical carcinomas." (PMID 25025847, 2014). "However, EFNA1 is increased when AP-2γ is highly expressed, which could be associated with resistance to cancer treatment." (PMID 35563688, 2022). "Collectively, our work uncovers Ephrin A1 as a functional ligand of EGFR and highlights the potential role of the Ephrin A1/EGFR/EMT regulatory axis in cancer metastasis." (PMID 39838173, 2025). "Another study focused on the GC hepatic premetastatic niche revealed that the ephrin A1-initialized YAP1-CCL2-Wnt/β-catenin axis bridged the malignant communications between cancer cells and hepatic stellate cells during GC hepatic metastasis." (PMID 40604818, 2025). "Specifically, EphA2 protein, which is sorted into sEVs secreted by senescent cells, can bind to ephrin-A1, a ligand highly expressed in various cancer cells, thereby promoting cancer cell proliferation through EphA2/ephrin-A1 reverse signaling." (PMID 40046513, 2025). "Classification and analysis of cancer types showed that EFNA1 was up-regulated in many tumors, most notably in BLCA." (PMID 35309935, 2022). "Based on the overall ESTIMATEscore, EFNA1/2/3/4 negatively correlated with non-cancer components in the majority of cancer types." (PMID 35945523, 2022). "In the majority of cancers, EFNA1, EFNA2, EFNA3, and EFNA4 were suppressed by stromal and/or immune components, whereas EFNA5 demonstrated different trends in the stromal and immune scores across different cancers." (PMID 35945523, 2022). "The correlation of EFNAs co-expression at transcriptome level in pan-cancer was first examined, and the results suggested a strong correlation between EFNA1, EFNA3, and EFNA4." (PMID 35945523, 2022).
cancer (continued). "Further integration analysis indicates that EFNA1 gene overexpression worsened the prognosis of patients with cancers, with the greatest impact on the prognosis of patients with ESCA." (PMID 34399788, 2021). "The results showed that the expression of EFNA1 mRNA and proteins was significantly higher in cancer cells than that of normal cells." (PMID 34399788, 2021). "Among 7563 samples from TCGA, the EFNA1 gene highly expressed in 15 samples with common cancers and endangered the prognosis of patients with tumors." (PMID 34399788, 2021). "The result showed that the expression of EFNA1 mRNA and protein was significantly higher in cancer cells than those in normal cells (P < 0.001)." (PMID 34399788, 2021). "For instance, DS-8895a, an anti-EphA2 mAb, inhibits the phosphorylation of EphA2 in cancer cell lines exposed to ephrin-A1." (PMID 32629797, 2020). "Ephrin A1’s expression pattern in cancer seems to differ from that of EphA2, with attenuation in a variety of aggressive tumors, particularly those overexpressing EphA2." (PMID 32811512, 2020). "Cleaved by cell matrix metalloproteases, soluble monomeric ephrin-A1 is released from cancer cells and drives EphA2 dimerization and signaling." (PMID 32629797, 2020). "It is considered that deficient cell-to-cell contact (commonly found in malignant cells) and insufficient levels of ephrin A1 on cancer cells reduce EphA2 phosphorylation." (PMID 32811512, 2020). "EVs secreted by fibroblasts and senescent epithelial cells bind to ephrin-A1, a molecule highly expressed in several types of cancer cells, and which promotes the proliferation of cancer cells through the reverse signaling of EphA2/ephrine-A1." (PMID 33227947, 2020). "sEV-associated EphA2 secreted from senescent cells binds to ephrin-A1, that is, highly expressed in several types of cancer cells and promotes cell proliferation through EphA2/ephrin-A1 reverse signalling." (PMID 28585531, 2017). "A deregulation of this system, and in particular of the activity of EphA2/ephrin-A1 signaling complex, has been related to cancer insurgence and progression." (PMID 26393553, 2015). "In vivo, however, ephrin-A1 is anchored to the outer membrane of the cell where it can function as substrate for cancer cells." (PMID 25644492, 2015). "In present study, we provided direct evidence that exposure to hypoxia resulted in elevated ephrin-A1 expression in cancer cells by western blot analysis." (PMID 24040255, 2013). "Ephrin-A1 is also known as an angiogenic factor, and plays pivotal roles in neovascularization in various cancers." (PMID 24040255, 2013). "Since ephrin-A1 has been reported to be cleaved from the surface of cancer cells by matrix metalloproteases, we also treated SKBR3 cells with the broad-spectrum matrix metalloprotease inhibitor GM-6001." (PMID 24348920, 2013). "Soluble EFNA1 is important for the growth of two cancer cell lines and contributes to the relocalization of EPHA2 away from cell-cell contacts which accompanies transformation." (PMID 20979646, 2010). "A positive role in promoting cancer has been confirmed experimentally in transgenic mice overexpressing EFNA1 in the intestinal mucosa, where EFNA1 enhances malignant progression in Apcmin/+mice." (PMID 20979646, 2010). "We conclude that the ability of cancer cells to release EFNA1 is an important step in EPHA2-mediated transformation in a subset of cancer cells." (PMID 20979646, 2010). "Since most of the EFNA1 in these cells is found in the media, this result suggests that soluble EFNA1 is required to promote the growth of these cancer cells." (PMID 20979646, 2010). "In fact, soluble EFNA1 is present in conditioned media from numerous cancer cell lines and was originally described as a soluble angiogenic factor induced by TNFα." (PMID 20979646, 2010). "Further work is required to determine how applicable these results are to other cancer cells that express soluble EFNA1." (PMID 20979646, 2010).
cancer (continued). "This provides evidence that the production the production of soluble EFNA1, at least some cancer cells lines, has physiological relevance." (PMID 20979646, 2010). "Our finding of EFNA1 in the conditioned media of HeLa cells indicates that, like many cancer cells, HeLa cells express EFNA1 in addition to EPHA2, and that some of the EFNA1 is released from the cell surface of these cells." (PMID 20979646, 2010). "It has been known since the early 90's that many cancer cell lines shed EFNA1 from their cell surface." (PMID 20979646, 2010). "Recent studies have elucidated the biological roles of SCNN1A and EFNA1 in cancer." (PMID 40787466, 2025). "However, the expression and function of Ephrin A1 in cancers are complex owing to cell-type dependent." (PMID 39838173, 2025). "Multiple studies have shown that Ephrin A1 was abnormally expressed in cancers." (PMID 39838173, 2025). "Notably, EFNA1 knockdown also suppressed the receptor tyrosine kinases signaling pathway, consistent with previous findings in other cancers." (PMID 39964764, 2025). "To explore whether EFNA1-SE regulation is a common feature across various cancer types, we conducted a pan-cancer analysis encompassing 24 primary cancer types." (PMID 39964764, 2025). "Interestingly, only a fraction (~25%) of these cancers manifested the EFNA1-SE signature, with detection rates ranging from 5% to 39%, notably lower than the 56% prevalence observed in CC samples." (PMID 39964764, 2025). "Notably, our study reveals that the EFNA1-SE signature is restricted to 7 of 24 cancer types, with a remarkably high prevalence (56%) in CC, underscoring the substantial heterogeneity of SE landscapes across different malignancies and individual patients." (PMID 39964764, 2025). "In patients with early-stage GC, we also observed the diagnostic ability of serum EFNA1 combined with MMP13 to distinguish cancer patients from normal controls (AUC 0.865, sensitivity 48.5%, specificity 90.2%) (Supplementary excel)." (PMID 38987376, 2024). "Compared with other cancers, EFNA1 and MMP13 were highly or moderately expressed in GC." (PMID 38987376, 2024). "For example, EVs from senescent stromal cells can enhance the proliferation of cancer cells by promoting the activation of the ephrin-A2 tyrosine kinase receptor, which interacts with overexpressed ephrin-A1 on the surface of the cancer cells, thereby boosting an Erk-dependent proliferation pathway." (PMID 37445973, 2023). "EFNA1 belongs to the subfamily of ephrins acting as the ligands for Eph receptors, and the interaction of EFNA1 with its most common receptor EphA2 is deemed crucial to the onset of malignant tumors, possibly via regulation of cell cytoskeleton and cell adhesion." (PMID 37449541, 2023). "EFNA1-5 showed significant differences in mRNA and protein levels across cancer types." (PMID 35945523, 2022). "Therefore, ephrin-A1 and the receptor, EphA2 are also promising targets for cancer therapy, and ephrin-A1 shows potential as a serum biomarker of cancer." (PMID 33804570, 2021). "EFNA1 expression in various cancers was analyzed according to the data in the TCGA database." (PMID 34399788, 2021). "Elucidating the mechanisms by which host ephrin-A1 impacts cancer relapse and metastasis may shed new light on novel therapeutic strategies." (PMID 32399207, 2020). "Soluble Ephrin A1 can promote metastasis in several cancer types." (PMID 32005975, 2020). "In addition, soluble Ephrin A1 has been reported to be secreted in conditioned media of several cancer cell lines and be detected in serum of cancer patients." (PMID 32005975, 2020). "Further elucidating the mechanisms by which ephrin-A1 in host cells impact cancer relapse and metastasis may enhance our understanding of the metastatic process and ultimately shed new light on novel therapeutic strategies." (PMID 32399207, 2020). "Therefore, we investigated the role of surface-attached and solubilized ephrin-A1 in determining cancer cell adhesion." (PMID 25644492, 2015).